TNF (tumor necrosis factor)
Diseases named in the same sentence as TNF in open-access papers (continued):
Sharing a sentence is not in itself a finding about the gene and the disease.
Stroke (continued). "Excess production of TNF alpha in the CSF of stroke survivors has been implicated in post-stroke pain." (PMID 37065345, 2023). "All three of these cytokines have been detected in the cerebrospinal fluid (CSF) of people after stroke, and elevations of TNF-α in CSF have been associated with poor clinical outcomes." (PMID 37266378, 2023). "The results also indicated that the TNF-alpha A allele was associated with risk of stroke with odd ratio (OR) = 2.22 and risk ratio = RR 2.47, p < 0.05." (PMID 37240845, 2023). "There were no significant sex differences in mean age, the distribution of APOE ε4 allele, stroke, hypertension, daily ActiGraph wear time, and serum concentrations of IL-6, IL-8, and TNF-α." (PMID 37491244, 2023). "TNF-inhibitors (TNFi) were effective in treating vasculopathy-associated symptoms and preventing stroke, but were hardly effective in the treatment of hematologic manifestations." (PMID 37277582, 2023). "The TNF-GA and TNF-GG + AA genotypes had a substantial impact on the risk of stroke in the over dominant inheritance model, with OR = 2.17, (95%) CI (1.00065 to 4.682), RR = 1.52 (0.951 to 2.43) and p = 0.048." (PMID 37240845, 2023). "Excess production of tumor necrosis factor alpha (TNF alpha) in the cerebrospinal fluid (CSF) of stroke survivors has been implicated in post-stroke pain." (PMID 37065345, 2023). "Tumor necrosis factor alpha (TNF alpha) plays a major role in causing and maintaining this inflammation in patients with vascular disease or post-stroke pain." (PMID 37065345, 2023). "There have been debates over the exact mechanism behind this phenomenon, however studies have established that anti-TNF treatments have reduced both the risk and prevalence of stroke." (PMID 37844090, 2023). "In the current study, we studied the associations of SNPs in the genes VWF, GSTs and TNF-alpha with stroke in the Saudi population." (PMID 37240845, 2023). "The TNF-GG and (GA + AA) genotypes were strongly associated with an increased risk of stroke in the dominant inheritance model (OR = 2.43, 95% CI (1.1418 to 5.2115), RR = 1.63 (1.0136 to 2.6319) and p = 0.021)." (PMID 37240845, 2023). "Elevated levels of inflammatory biomarkers, such as C-reactive protein (CRP), interleukin-6 (IL-6), and tumor necrosis factor-alpha (TNF-α), have been associated with poor stroke outcomes, including increased mortality, disability, and recurrent stroke risk." (PMID 37468969, 2023). "Even though some studies reported no important association between TNF-α levels and the risk of stroke, other studies found that early TNF-α plasma levels correlate with stroke outcome." (PMID 36745280, 2023). "Evidence suggested that TNF-α/IFN-γ synergy amplifies senescence-associated inflammation and that TNF-α antagonism can rescue the effect of aging on stroke." (PMID 37742294, 2023). "The association of TNF-α rs1800629 G > A genotypes between stroke patients and controls was statistically significant (p = 0.038)." (PMID 37240845, 2023). "Our results demonstrated that the TNF-alpha rs1800629 G > A was associated with stroke in our cases, and that the GA genotype and the A allele of TNF-alpha rs1800629 were associated with stroke development." (PMID 37240845, 2023). "TNF alpha levels correlate with the volume associated with the brain infarct and sharply increase and persist immediately after the stroke." (PMID 37065345, 2023). "The results indicated a possible connection between the TNF-alpha-GA genotype and enhanced stroke susceptibility in the codominant model, with OR = 2.22, (95%) CI = (1.031 to 4.808), RR = 1.54 (0.9624 to 2.464) and p = 0.041." (PMID 37240845, 2023). "In stroke outcomes, TNF-α is associated with epileptic seizures, movement disorders, spasms, aphasia, pain, depression, and cognitive impairment." (PMID 35265224, 2022). "TLR4 mediates the activation of innate responses in monocytes, such as NF-κB activity and TNF-α synthesis, and are associated with worse outcomes in stroke patients." (PMID 34711943, 2022).
Stroke (continued). "Several studies have reported that higher post-stroke TNF-α levels are associated with poorer long-term outcomes or larger infarct size." (PMID 35631536, 2022). "Systemic elevations of IL-6 and TNF-α have been reported to be associated with cognitive decline and stroke recurrence." (PMID 35467483, 2022). "In a long-term follow-up study, serum TNF-α concentrations were associated with poor long-term outcomes after stroke." (PMID 36211352, 2022). "In accordance with the present results, previous studies revealed that increased concentration of inflammatory biomarkers, including CRP, IL‐6, and TNF‐α, is associated with increased risks of the occurrence and worse prognosis of stroke." (PMID 35588444, 2022). "These deficits were even more pronounced in stroke patients who developed stroke-associated infections, with further reductions in TNF-α and increased IL-10." (PMID 38566903, 2022). "The generation of tumor necrosis factor (TNF)-α in monocytes has been independently associated with stroke." (PMID 36247122, 2022). "Based on several robust pieces of evidence, changes in TNF-α were associated with stroke injury and stroke recovery." (PMID 35265224, 2022). "In particular, among the studies with MI or stroke as outcome, the use of TNF inhibitors was associated with a 41% relative risk reduction of MI and a 43% reduction of stroke." (PMID 36352850, 2022). "There is considerable evidence that TNF-α is significantly associated with ischemic stroke, which further increases sharply in the acute stage of stroke, resulting in serious tissue damage." (PMID 35559267, 2022). "It has also been shown that higher levels of IL-6 in the acute phase of stroke and on the first and seventh days, and TNF-α during onset, were associated with poorer early and late prognosis in patients treated with intravenous thrombolysis." (PMID 36142524, 2022). "According to some strong evidence, TNF-α expression is associated with stroke injury and stroke recovery." (PMID 36389810, 2022). "Further, inflammatory markers such as c-reactive protein, tumor necrosis factor-alpha and interleukins are increased in patients with anemia and associated with an adverse prognosis after stroke." (PMID 34207841, 2021). "The M1-type macrophage secretes pro-inflammatory factors, such as reactive oxygen species (ROS), tumor necrosis factor-alpha (TNF-α), and interleukin 1 beta (IL-1β), which are well documented to damage the AS plaque stability and cause stroke." (PMID 34820428, 2021). "Inflammatory cytokines (TNF-α and IL-1β) and adhesion cell molecules are useful to evaluate the risk of stroke and have fundamental roles in the pathophysiology of brain ischemia." (PMID 35126096, 2021). "A meta-analysis previously estimated a 30% reduction in risk of cardiovascular events with TNF-α inhibitors in RA, with protective effect specifically for MI and stroke." (PMID 34504395, 2021). "A particular role of TNF-TNFR1 signaling in the etiopathogenesis of stroke is suggested by genome-wide association studies that found a polymorphism in the TNF gene that increases susceptibility to ischemic stroke." (PMID 33918875, 2021). "Larger strokes have been shown to be associated with lower levels of TNF-α, IL-1β, P-selectin, and ICAM-1 as compared to lacunar strokes." (PMID 35008440, 2021). "In rodents undergoing permanent transient middle cerebral artery occlusion (pMCAO), global or myeloid cell-specific TNF-α KO is associated with bigger infarct size and worsened post-stroke deficits." (PMID 33770265, 2021). "A patient with substantial portal hypertension and esophageal varices had resolution over the course of 6 years on anti-TNF therapy further emphasizing a benefit to anti-TNF therapy beyond stroke risk reduction." (PMID 35095905, 2021). "In the present work, studies have shown that Induction of stroke caused a significant increase in TNF-a, IL-1B, and MDA levels compared to the control group (p < 0.001)." (PMID 34600570, 2021).
Stroke (continued). "Treatment with anti-TNF agents should be strongly considered for all as they significantly reduce a patient’s risk for stroke and other complications of the disease." (PMID 35095905, 2021). "Polymerase δ-interacting protein 2 was also upregulated in astrocytes following a stroke, which caused an increases in the extravasation of Evans blue by inducing the expression of TNF-α, IL-6, MCP-1, VEGF, and MMP." (PMID 34248961, 2021). "Increased TNF-α levels in CSF and blood are significantly associated with stroke outcome assessments including the Barthel Index and Scandinavian Stroke Scale (SSS)." (PMID 34829993, 2021). "Here we found that those patients with increased risk of long-term death after stroke showed higher baseline levels of TNF-R1, reinforcing the crucial role of the TNF signaling pathway in stroke prognosis." (PMID 33578805, 2021). "These experimental studies are further corroborated by VaD and post-stroke patient studies, which both show increases in TNF-α, IL-1β and IL-6 within the CSF/serum that are associated with cognitive decline." (PMID 34884906, 2021). "We tested the effects of MEDS-23 on levels of the inflammatory mediators IL-6 and TNF-α in brains of post-stroke rats to elucidate a possible association between its antipyretic effect and its correlation with neuro-inflammation." (PMID 35053779, 2021). "Through enrichment analysis, we identified the functions of active ingredients in directly or indirectly regulating a number of pathways associated with the treatment of stroke, including TNF, cAMP, IL-17, and MAPK signaling pathways." (PMID 34754318, 2021). "Few studies suggest that the reduced ex vivo TNFα and interferon-gamma-inducible protein 10 (IP-10) synthesis after endotoxin challenge is associated with poor functional outcome after stroke." (PMID 31906994, 2020). "Plasma TNF levels are increased in stroke patients compared with controls, and common polymorphisms of the TNF gene promoter leading to increased circulating TNF levels appear to be associated with cardiovascular risk factors and ischemic stroke in Asians." (PMID 32503645, 2020). "The magnitude of lymphocyte TNF-α production in response to MBP during the acute phase of stroke was associated with poor stroke outcomes." (PMID 32719588, 2020). "Elevated levels of circulating IL-6 and CRP as well as reduced TNFα production ex vivo are associated with poor outcome after stroke." (PMID 32107751, 2020). "Recently, we reported that the reduced release of TNFα and IP-10 is independently from age and stroke severity associated with worse prognosis after stroke." (PMID 31906994, 2020). "The larger increase in apoptosis observed in male compared to female cells in response to TNFα is consistent with other observations of divergent cellular pathways associated with cell survival in stroke." (PMID 31118073, 2019). "Our studies indicate that the levels of two major pro-inflammatory cytokines associated with stroke injury, TNF-α and IL-6, were elevated following MCAO injury." (PMID 31354401, 2019). "Tumor necrosis factor alpha was chosen, because a few studies showed an associated between this cytokine and post-stroke infections." (PMID 29669581, 2018). "In the process of stroke, I/R induced the production and secretion of apoptosis and such inflammation associated cytokines as TNF-α, IL-1β and IL-6." (PMID 29383171, 2017). "Tumor necrosis factor-α (TNF-α): TNF-α is a well-known inflammatory factor associated with worsened clinical outcomes after stroke and exacerbations of infarct size in pre-clinical models." (PMID 28115020, 2017). "TNF-α has been implicated in the pathogenesis of a wide number of neurological disorders that develop both acutely, as in traumatic brain injury and stroke, and chronically, as in Alzheimer’s disease and Parkinson’s disease." (PMID 27445694, 2016).
Stroke (continued). "After stroke, inflammatory cytokines such as tumor necrosis factor (TNF-alpha), interleukin (IL)-1, IL-6 and IL-12 have been implicated in the cascade leading up to BBB disruption and neurovascular uncoupling." (PMID 27374823, 2016). "The relevance of the present study was underlined by investigating glial activation, TNF and TNF receptor expression in human autopsy material from stroke patients." (PMID 27384243, 2016). "IL-1β and TNF-α have been associated with exacerbation of injury in stroke while IL-6 has been found to be neuroprotective." (PMID 26074992, 2015). "We also discuss data supporting TNF alpha associated inflammation in traumatic brain injury, stroke, and spinal disc associated radiculopathy." (PMID 26664821, 2015). "Several proinflammatory factors have been reported to be active in recurrent stroke, including IL-6, TNF-α, lipoprotein-associated phospholipase A2, C-reactive protein, and fibrinogen." (PMID 26576074, 2015). "SP-D is known to bind TLR2 and TLR4, as well as SHPS-1/SIRPα that are all expressed on and linked to induction of TNF in microglia and macrophages and involved in stroke." (PMID 25038795, 2014). "Abundant studies proved the association between stroke and the increase of various proinflammatory cytokines, including members of interleukin (IL), tumor necrosis factor (TNF), and interferon (IFN) families." (PMID 24744682, 2014). "Tumor necrosis factor (TNF) is an immunomodulatory molecule known to be implicated in central nervous system (CNS) insults such as stroke." (PMID 25498129, 2014). "Tumor necrosis factor (TNF), which exists in both a transmembrane (tm) and soluble (sol) form, is known to sustain complex inflammatory responses associated with stroke." (PMID 25498129, 2014). "Increasing evidences have demonstrated the important role of TNF-α in the development of ischemic stroke, but studies examining the possible association with stroke or direct functional effects of polymorphisms in TNF-α have been contradictory." (PMID 23050663, 2012). "In our next case–control study and meta-analysis, we confirmed the significant association between TNF-α promoter variant -308G/A and stroke in the Asian population." (PMID 23050663, 2012). "TNF-α has been implicated in the pathogenesis of a wide number of neurological disorders, including AD, PD, stroke and head trauma." (PMID 22642825, 2012). "Up-regulated TNF-α expression has also been found in various neurodegenerative diseases such as cerebral malaria, AIDS dementia, Alzheimer's disease, multiple sclerosis, and stroke, suggesting a potential pathogenic role of TNF-α in these diseases as well." (PMID 21298033, 2011). "LPS-preconditioned mice also showed marked resistance to brain injury caused by intracerebral administration of exogenous TNF-α after stroke." (PMID 21982558, 2011). "Higher stroke severity, larger hematoma volume, larger edema volume, intraventricular extension, mass effect, and higher baseline IL-6 and TNF-α were associated with poor clinical outcome." (PMID 20936104, 2010). "Proinflammatory cytokines have been implicated in exacerbating the damage in stroke by increasing neuroinflammation, with particular attention paid to TNF-α." (PMID 20190963, 2009). "Although TNF‐α shows consistent associations with stroke risk, clinical translation currently favors measuring downstream inflammatory markers (e.g., hs‐CRP and IL‐6) for prediction; TNF‐α nevertheless strengthens multimarker signatures reflective of vascular inflammation." (PMID 41567175, 2026). "In CV risk subgroups, TNF-α inhibitors were associated with a reduced risk of stroke (aHR, 0.36; 95% CI, 0.14–0.98) in the high-risk group, accompanied by an increased risk of HCV infection (aHR, 7.51; 95% CI, 1.50–37.56) and CKD (aHR, 2.08; 95% CI, 1.21–3.58)." (PMID 41007780, 2025).
Stroke (continued). "Of note, elevated TNFα levels are linked to worse outcomes in stroke patients, and overwhelming preclinical evidence shows that TNFα signaling increases brain damage following stroke through sustained neuroinflammation, the disruption of BBB function, and the promotion of neural apoptosis." (PMID 40362325, 2025). "To explore underlying mechanisms, we measured serum levels of Brain-Derived Neurotrophic Factor (BDNF), a key marker of neuroplasticity, and pro-inflammatory cytokines Tumor Necrosis Factor-alpha (TNF-α) and Interleukin-6 (IL-6), which are implicated in post-stroke neural injury and repair." (PMID 40904820, 2025). "Notably, the pathways responsible for inflammatory signaling, such as TNF-α, Stat5, IL-6, and Jak-stat were decreased in MiD mice compared to MiS stroke mice, suggesting reduced brain inflammation in deficiency of gut microbiota." (PMID 40410847, 2025). "Notably, biomarkers like tumor necrosis factor-α (TNF-α), C-reactive protein, and interleukin-6 (IL-6) are robustly linked to higher occurrences of stroke, coronary heart disease, and death from cardiovascular disease." (PMID 40270516, 2025). "TNF-alpha inhibitors, such as infliximab and adalimumab, effectively reduce systemic inflammation and may lower stroke risk in patients with IBD." (PMID 40125129, 2025). "Furthermore, adequate sleep reduces levels of inflammatory cytokines, such as interleukin-6 (IL-6) and tumor necrosis factor-alpha (TNF-α), which have been linked to poor stroke outcomes." (PMID 40004843, 2025). "Our data from serial RNA sequencing of whole blood suggested that active tVNS increased expression of genes encoding for TNF-α signaling, which are typically supressed after middle cerebral artery occlusion in experimental murine models and humans after stroke." (PMID 41455014, 2025). "SGLT2 inhibitors demonstrate robust benefits for heart failure and cardiovascular mortality across large CVOTs, with parallel reductions in IL-6, TNF-α, and oxidative stress that may translate to stroke and dementia risk reduction." (PMID 41462689, 2025). "Another miRNA linked to neuronal inflammation is miR-128 which was found to increase the levels of TNF-α and promote neuronal apoptosis after stroke Similarly, higher miR-19a-3p levels were associated with increased TNF-α production and enhanced cerebral I/R injury." (PMID 38909168, 2024). "Studies have shown that microglia can secrete inflammatory factors such as TNFα and IL-6 and cause damage to the blood-brain barrier in stroke, while certain CNS fibroblasts are involved in the repairing process of damaged tight junctions and management of infarct volume." (PMID 39520909, 2024). "The relationship between genetic variation in TNF-α and stroke risk thus remains uncertain." (PMID 39628323, 2024). "Moreover, in a 1-year follow-up assessment of blood biomarkers in patients who experienced stroke (64.5 ± 9.5 years), higher TNF-α and IL-1β levels were associated with poor outcomes at 1-year post-stroke." (PMID 37728582, 2024). "Moreover, a Mendelian randomization study revealed evidence of a causal association between TNF-α levels and cardiovascular events (coronary artery disease and stroke)." (PMID 39367448, 2024). "Additionally, the prognosis of stroke patients has shown positive correlations with the expression levels of H19 and TNF‐α in the blood, suggesting their potential as diagnostic indicators with high sensitivity and specificity." (PMID 39049714, 2024). "VER-induced increase of IF-10 and inhibition of TNF-α expression are not only associated with endothelial progenitor cells mobilization, but also play a significant role in anti-inflammation and neuroprotection during the acute phase of stroke." (PMID 39502386, 2024).